MMP14 (matrix metallopeptidase 14)
Diseases named in the same sentence as MMP14 in open-access papers (continued):
Sharing a sentence is not in itself a finding about the gene and the disease.
tumor (continued). "Similar to resected specimens, in biopsies, MMP14 expression in CAFs and tumour nests and its expression based on the co-scoring system revealed high concordance with MMP14 expression at the ENE site." (PMID 36765296, 2023). "Invadopodia, characterized by co-localization of cortactin and F-actin, and high MMP14 expression in invadopodia are essential for tumor cell invasion." (PMID 37686118, 2023). "(b) Plot shows quantification of A431 tumour growth with the indicated manipulations of MMP14 and CTNNA1." (PMID 36892272, 2023). "MMP14 expression in tumour nests and CAFs and its overexpression at the tumour–stromal interface significantly correlated with the presence of ENE." (PMID 36765296, 2023). "This inhibitory effect of TEPA on TGF-β is also evidenced by a significant decrease in VIM, MMP-9 and MMP-14, which play a key role in promoting tumor invasion." (PMID 37480151, 2023). "Following carboplatin treatment, CAFs increased their expression of numerous MMP genes (Mmp2, Mmp3, Mmp13, Mmp14, Mmp27); proteases involved in the degradation of the tumor-supporting matrix." (PMID 37660083, 2023). "BM-MSC-exos carrying miR-1228 and MMP-14 have been co-cultured with SGC-7901 and MGC-823 GC cells, confirming that miR-1228 is a tumor suppressor that targets and downregulates MMP-14—a protein coding gene involved in metastasis." (PMID 37189649, 2023). "Results showed that the protein levels of N-cadherin, Vimentin, Slug, p-HER2, p-EGFR, p-ERK1/2, MMP9 and MMP14 increased significantly in PLC/PRF-5LL−37 xenograft tumor; while significantly decreased in PLC/PRF-5LL−37 xenograft receiving si-LL-37 treatment." (PMID 36656313, 2023). "MMP-9 and MMP-14 were found in the cytoplasm of cancer cells and were significantly enhanced in metastatic lymph nodes compared to the primary tumour." (PMID 38203696, 2023). "We hypothesize that the overexpression of MMP14 might have certain advantages over the expression of secreted heparanase or the systemic application of lysyl oxidase inhibitors, as MMP14 is a membrane-anchored protein lowering the risk of structural changes outside of the tumor tissue." (PMID 37139603, 2023). "PLAU and MMP14 were highly expressed in both tumor cells 3 and CAFs but were also consistently detected in TAMs and tumor cells." (PMID 37007745, 2023). "Actin rearrangement changes the original cell morphology and adhesion ability, which is a necessary condition for tumor invasion and metastasis, and MMP14, as well as cortactin, plays a key role in the formation of invadopodia." (PMID 37686118, 2023). "MMP14 is a membrane-type-1 MMP expressed at the tumour membrane and cleaves gelatine, fibronectin, and laminin and regulates invadopodium development." (PMID 36765296, 2023). "Several studies have demonstrated that overexpressed MMP14 contributed to tumor cells invasion and metastasis." (PMID 37007125, 2023). "Quantification of the immunoblot results demonstrates a statistically significant increase in RECK expression and reduction of MMP14 in rTIMP2 treated wt tumor-bearing mice compared with vehicle control (HBSS) treated wt tumor-bearing mice." (PMID 38234759, 2023). "qRT-PCR analysis with PANC-1 and BxPC-3 cells confirmed that circEIF3I KD inhibited the mRNA expression of MMP2, MMP9 and MMP14, which are closely related to tumour invasion and metastasis." (PMID 37689715, 2023). "We detected the expression of MMP14 in dissected HepG2 tumor tissues as indicative of the MMP14‐responsive release of melittin." (PMID 38023709, 2023). "Increased expression of MMP14 in tumor cells enhances the growth, invasion, and metastasis of tumor." (PMID 36192574, 2023). "MMP14 expression in tumour nests and CAFs in primary TSI showed a significant association with clinicopathological pENE+, TME activity-related features (TB, DR, and TILs), and invasiveness and metastatic features." (PMID 36765296, 2023).
tumor (continued). "(c) Table shows quantification of mice with primary tumours and mice with lymph node metastases when injected with A431 cells with the indicated manipulations of MMP14 and CTNNA1." (PMID 36892272, 2023). "MMP14 overexpression in tumour nests and CAFs was more often observed at metastatic LNs with ENE than in those without ENE and at the TSI in the primary and ENE sites; the expression at these sites was similar, even in biopsies." (PMID 36765296, 2023). "The tumour immune environment contained high M2 macrophage infiltrate linked with MMP2, MMP14, TGFB1 and CCL2 expression, representing an immune suppressive environment." (PMID 35637530, 2022). "The expression of CCL20, CD70, PCDH7, DCBLD2, and MMP14 genes were remarkably more elevated within LUAD samples than adjacent non-tumorous tissues, where PIK3R5, RNF144B, BTG2, CD69, and MEP1A genes were the opposite." (PMID 36497225, 2022). "Matrix metalloproteinase 14 (MMP14), a member of the membrane‐type MMP family, is strongly associated with tumour metastasis." (PMID 34890108, 2022). "MMP-2, MMP-9 gelatinases, and membrane-bound MT1-MMP (aka MMP14) are overexpressed in the OvCa tumor microenvironment (TME) as compared to normal and benign ovarian tissue." (PMID 36077371, 2022). "An anti-MMP-14 inhibitory antibody (DX-2400) identified using a human Fab displaying phage library demonstrated inhibitory effect on primary tumor growth and incidence of metastasis to the lung and liver in a MDA-MB-231 orthotopic model." (PMID 36741729, 2022). "Subcutaneous xenograft nude mouse models confirmed that the growth of tumours was weakened by knocking down the expression of MMP14 and INHBA." (PMID 35150061, 2022). "Tumor-derived eCAFs (Cluster 3) are characterized by high expression of genes associated with tumor invasion (MMP14, LOXL2, and POSTN), indicating that eCAFs constitute an essential component of the TME for tumor metastasis." (PMID 34976204, 2022). "These tumor-reactive antibodies can target MMP14 on the surface of tumor cells and induce NK cell-mediated antibody-dependent cellular cytotoxicity (ADCC)." (PMID 35967441, 2022). "Tumor samples presented extensive homogenous protein levels of both ENG/MMP14 on the TMA sections and thus were evaluated by intensity only." (PMID 35955799, 2022). "MMP-14, a member of the matrix metalloproteinase family, promotes tumor invasion by degrading collagen." (PMID 36382024, 2022). "When MMP-14 was analyzed, its expression was readily detectable in all normal skin samples, whilst in 9/9 tumor samples (100%), a lower expression was evident and confirmed by densitometric analysis." (PMID 36518899, 2022). "The first prospective predictive marker of tumor behavior in commonly available biological material appears to be the MMP-14 enzyme." (PMID 36672540, 2022). "Of clinical relevance, tumor-surrounding adipocytes in obese patients are more prone to activating the HIF-1α/MMP-14 signaling pathway, and the expression of NOX5 and MMP-14 is upregulated in the invasive front of tumors, the side proximal to the PPAT." (PMID 35406450, 2022). "Exosomes were confirmed by the expression of exosome marker, the tumor susceptibility gene (TSG101), while MMP14 was detected in the portion of exosome pellets, but not in the supernatant." (PMID 35223528, 2022). "The MMP family member MMP14 has the functions of regulating cell growth, tumor invasion and metastasis, and key gene expression." (PMID 35891968, 2022). "The second possibility is that tumor cells express CLIC2 that binds to MMP14 intracellularly while inhibiting the enzyme activity." (PMID 36230813, 2022). "MMP-14 is found in higher concentrations in many tumor tissues and is involved in tumor progression, angiogenesis, and metastasis." (PMID 35729613, 2022). "Particular inhibitory antibodies to MMP-9 and MMP-14 have been developed and shown to be effective in inhibiting tumor growth and metastasis, but their clinical efficacy is currently uncertain." (PMID 36700222, 2022).
tumor (continued). "MT1-MMP (MMP14) is considered to play a key role in the early stages of tumor invasion and cancer progression." (PMID 35008401, 2022). "MMPs, in particular MMP-2, MMP-9 and MMP-14,57 facilitate tissue remodelling, a vital process during neo-angiogenesis and tumour progression." (PMID 33758004, 2022). "A variety of MMPs, including MMP-2, MMP-9 and MMP-14, can degrade the basal layer of capillaries and promote exosmosis of tumor cells." (PMID 36776395, 2022). "Being a member of the first membrane matrix metalloproteinases (MMPS), MMP14 has been shown to promote extracellular matrix (ECM) degradation to accelerate tumor cell migration, inflammation, invasion, angiogenesis and metastasis." (PMID 36186418, 2022). "Of note, however, the expression level of MRC2, an M2-type immunosuppressive and tumorigenic macrophage–related gene, was most strongly correlated with that of MMP14, also implicating M2-TAMs in MMP14-related tumor progression." (PMID 36052235, 2022). "Given its impact on tumor angiogenesis, monitoring MMP-14 provides strategic insights on cancer severity and treatment." (PMID 36291022, 2022). "To determine the cell lineages responsible for MMP14-related tumor recurrence, we evaluated the relation of RFS to MMP14 expression in different cell types." (PMID 36052235, 2022). "Fourth, MMP14 exists as active and inactive forms, with only the former being thought to contribute to the control of tumor growth and cancer cell invasion." (PMID 36052235, 2022). "MMP14 expression was detected predominantly in tumor cells and CAFs, although it was also apparent in TAMs and TILs." (PMID 36052235, 2022). "On the basis of our analysis of TCGA gene expression data, we spatially evaluated multiple cell compartments including CAFs, M1- and M2-TAMs, and tumor cells in addition to MMP14 expression in individual FFPE tumor tissue sections by 12-color mIHC." (PMID 36052235, 2022). "In particular, in the U87MG_mCherry cohort, Musashi 1 and MMP14 staining revealed only a few positive cells, mainly in the tumor border." (PMID 36230481, 2022). "For example TIMP-2 binds to MMP-14 on the tumor cell surface, and this binding induces cell proliferation mediated through the subsequent activation of extracellular-regulated kinases (ERK) 1/2." (PMID 34204372, 2021). "At the same time, the results of this study show that MMP14 has an important effect on the prognosis and immune infiltration of many tumors, which provides a new direction for tumor research." (PMID 34604053, 2021). "The CD204+ GAMs co-expressed proteins related to tumor aggressiveness including matrix metallopeptidase-14 (MMP14) and hypoxia-inducible factor-1α (HIF-1α)." (PMID 34071306, 2021). "Of these, ADM, DCBLD2, EREG, ITGA5, MIF, MMP14, and TREM1 were associated with poor prognosis and significantly increased in tumor, while BTG2 was related to favorable prognosis and decreased in tumor." (PMID 35002712, 2021). "It has been reported that the increased expression and activity of MMP14 in tumor cells are directly related to their enhanced cell migration ability." (PMID 34604053, 2021). "For instance, a recent report suggests that TMZ treatments launch a tumor escape mechanism in serum-free conditions through matrix metalloproteinase-14 (MMP14) upregulation and activation of GSC stemness." (PMID 33525678, 2021). "We found that, the transcriptional level of MMP1, MMP3, MMP7, MMP9–MMP12, and MMP14 in tumor were significantly upregulated, both in public database and in our samples." (PMID 34804973, 2021). "During angiogenesis, tip cells at the leading edge of the neovasculature transiently regulate matrix remodeling via MMP-14, while, in immature tumor vessels, MMP-14 expression is more diffuse." (PMID 35008569, 2021). "By identifying the precise mechanisms whereby MMP-14 stimulates tumour growth, anti-MMP agents that have a targeted action are developed and can be tested in a minimal residual disease setting after debulking." (PMID 34344453, 2021).
tumor (continued). "It has been reported that high levels of matrix metalloproteinases, such as MMP-1, MMP-2, MMP-9, and MMP-14, produced by tumor cells participate in VM37." (PMID 33850110, 2021). "In the protein level, MMP14 was significantly upregulated in tumor tissue both in the UALCAN database and in patients 2, 3, 7, 9, 10, 11, and 12 of our own subjects." (PMID 34804973, 2021). "MMP-14 mRNA expression in tumour cells of the metastasis correlated with poor survival, while expression in the stromal cells correlated with longer survival." (PMID 34344453, 2021). "In both mouse and human NSCLC, MMP14 is significantly upregulated in intratumoral myeloid compartments and tumor epithelial cells." (PMID 34976811, 2021). "In lung tumor, MMP14 was observed to enhance the EGFR signaling to promote tumor metastasis and growth." (PMID 34868395, 2021). "In clinocopathological research, MMP-14 expression is found in most tumours with characteristics of poor prognosis but this immunohistochemical MMP-14 determination does not seem to be an independent predictor of prognosis." (PMID 34344453, 2021). "Knockout or inhibition of CXCL10/TLR4 signaling significantly reduced the tumor growth with decreased monocytic MDSCs and MMP14 in the mouse tumor recurrent model." (PMID 33990548, 2021). "At the same time, some studies have shown that MMP14 is involved in normal physiological functions and tumor-related processes such as cell migration, invasion, metastasis, angiogenesis, and proliferation." (PMID 34604053, 2021). "In the transcriptional level, MMP14 was significantly upregulated in tumor tissue both in the public database and our own subjects." (PMID 34804973, 2021). "CCL20, MMP14, and PCDH7 were upregulated in LUAD tumor tissues and linked to poor clinical outcomes, while BTG2, CD69, GPC3, IL7R, and NMUR1 are the opposite." (PMID 34881236, 2021). "We found that compared with normal tissue, MMP14 expression differed in 23 kinds of cancer, and high expression of MMP14 and tumor MMR, MSI, and DNA methylation were closely related to TMB." (PMID 34604053, 2021). "DX-2400 is a high-affinity, highly specific inhibitor of MMP-14 that inhibits tumor development and metastasis in vivo animal models of breast cancer and melanoma." (PMID 34912809, 2021). "KCs also secrete hepatocyte growth factor (HGF), VEGF, and matrix metalloproteinases (MMPs) such as MMP-9 and MMP14 that promote tumour cell invasion in the parenchymal space as well as tumour cell proliferation and angiogenesis." (PMID 33669775, 2021). "We found that the protein level of MMP2, MMP7, MMP9, MMP12, and MMP14 in the tumor tissue were basically higher than that in the normal tissue." (PMID 34804973, 2021). "MMP14 (also known as membrane type-I matrix metalloproteinase, MT1-MMP) can be expressed across a mix of fibroblasts, MΦ, and tumor cells." (PMID 33391974, 2021). "Lumican was shown to protect collagen against MMP-14 proteolysis, leading to inhibition of tumor progression." (PMID 34638415, 2021). "MMP14 is highly correlated with tumor prognosis and immune invasion and affects the occurrence and progression of many tumors." (PMID 34604053, 2021). "Sato and his group firstly reported MMP14 as a transmembrane protein which can promote the potential metastasis of tumor cells via activating pro-MMP2." (PMID 34868395, 2021). "In conclusion, this study explored the important role of MMP14 in tumor prognosis, and the expression of MMP14 was highly correlated with tumor immune invasion, especially with obvious tumors, including BRCA, CESC, COAD, LGG, and PCPG." (PMID 34604053, 2021). "It has also been reported that as a tumor promoter, MMP14 acts by inhibiting cell adhesion molecules, and tumor necrosis factor-α (TNF-α) is one of its acting factors." (PMID 34604053, 2021). "In CRC samples, immunostaining for MMP-7, MMP-14 and TIMP-1 were localized primarily in tumor cells, but also in stromal cells (cancer-associated fibroblasts (CAF) as well as MICs)." (PMID 33946534, 2021).
tumor (continued). "Lumican, a small leucine-rich proteoglycan (SLRP) of the extracellular matrix (ECM), displays anti-tumor properties through its direct interaction with MMP-14." (PMID 34638415, 2021). "First, we used gene expression profile data to analyze the relationship between MMP14 expression and tumor prognosis in 33 tumors in TCGA database." (PMID 34604053, 2021). "Membrane type 1 matrix metalloproteinase (MT1-MMP, and MMP-14) is a cell membrane-associated endopeptidase involved in degradation of the ECM of stromal cells and facilitates cell migration, tumor invasiveness, and resistance to chemotherapy." (PMID 34885196, 2021). "Man-MPs overexpressed MMPs, such as MMP9 and MMP14 proteins, leading to the efficient degradation of tumor collagen." (PMID 33469052, 2021). "It is reported that MMP14 act as a tumor promoter and HDGF is involved in the regulation of cell apoptosis, angiogenesis, invasion and metastasis and they were targeted by miR-195-5p." (PMID 33906322, 2021). "Considering MMP/TIMP expression, tumor budding showed a positive and significant association with MMP-11 (p = 0.029), MMP-14 (p = 0.024), and TIMP-1 (p = 0.021) expression by CAFs and MMP-14 expression by tumor cells (p = 0.034)." (PMID 33669393, 2021). "For example, lamstatin (NC1), the C-terminal domain of the α5 chain of type IV collagen, inhibits tumor cell migration by down-regulating both αvβ3 integrin and MMP-14." (PMID 35008569, 2021). "MDA–MB-231 cells express high levels of MMP14, which has important roles in driving tumor growth, invasion, and angiogenesis in mouse xenograft studies." (PMID 34415995, 2021). "Similar associations were found for other claudins and MMPs, including MMP14 (MT1-MMP) which is essential for matrix degradation during tumor invasion." (PMID 34674701, 2021). "A promising new development is a MMP-14 specific nanoprobe that facilitates in vivo detection of MMP-14 tumour cells." (PMID 34344453, 2021). "In the clinicopathological analyses, upregulated MMP11, MMP14, MMP16, MMP17, MMP19, and MMP23B were significantly associated with a higher tumor stage." (PMID 34804973, 2021). "MMP-14 plays a key role in detaching cells from the primary tumour and forming multicellular aggregates (MCA) that subsequently adhere to and invade mesothelial monolayers." (PMID 34344453, 2021). "MMP14 is involved in activation of the proMMP2 and also plays a role in activation of mechanisms of tissue matrix remodeling, tumor angiogenesis, cell signaling, migration, and inflammation." (PMID 34572485, 2021). "Since then, several new targeted agents against MMPs have been developed including antibodies and one of these new agents is a MMP-14 specific nanoprobe that facilitates in vivo detection of MMP-14 tumour cells." (PMID 34344453, 2021). "This evidence suggests that MMP14 can modulate the infiltration of immune cells, perhaps by regulating or recruiting immune cells, and thus play a role in tumor regulation." (PMID 34604053, 2021). "In studies conducted on mouse mammary gland cancer cell lines 4T1 and E0771, it was proved that anti-MMP14 antibody administration inhibited tumor growth in both models." (PMID 32887237, 2020). "In the late stage of tumor progression (day 28), there was a reduction in the levels of Csf1, Mmp14, Nedd9, Nf2, Plaur, and Tgfb1 genes by all the investigated compounds." (PMID 32887237, 2020). "After the correlation adjustment based on tumor purity, results showed that the MMP14 expression level remarkably correlated with most immune markers." (PMID 32974187, 2020). "While the vast majority (86–97%) of microglia showed expression of individual MT-MMPs, we observed significant differences in the proportions of MMP expression in tumor cells: MMP14 was produced by 54%, MMP16 by 80%, and MMP17 by 90% of tumor cells." (PMID 32872536, 2020).